DPP4 (dipeptidyl peptidase 4)
Diseases named in the same sentence as DPP4 in open-access papers (continued):
Sharing a sentence is not in itself a finding about the gene and the disease.
injury (9 papers, 2014 to 2025). Damage inflicted on the body as the direct or indirect result of an external force, with or without disruption of structural continuity. "Increases in circulating DPP4 during chronic liver injury can be due to both cell death and the loss of hepatocyte polarity, which causes DPP4 to be shed from all cell surfaces rather than exclusively into the bile canaliculus." (PMID 34771657, 2021). "Transgenic mice with hepatocyte-specific DPP4 overexpression fed with high-fat diet (HFD) displayed greater hepatic fat content and signs of liver damage than wild type; conversely, DPP4 knocking out was shown to protect mice from experimentally-induced liver injury." (PMID 32852705, 2021).
keloid (9 papers, 2021 to 2025). An irregularly shaped, elevated mark on the skin caused by deposits of excessive amounts of collagen during wound healing. "In this study, we first evaluated the distinctive functions of DPP4+ and DPP4− fibroblastic cells from human keloids, assessing their potential for multidirectional differentiation." (PMID 41395508, 2025). "It is likely that elevated DPP4 levels in keloids inhibit the adipogenic capacity of IGF1, which can be restored by sitagliptin." (PMID 41395508, 2025). "Selective inhibition of fibroblast- and keratinocyte-derived DPP-4/CD26 has been proposed as a therapeutic tool to inhibit skin fibrosis and prevent proliferative scarring and keloid scar formation." (PMID 40843763, 2025). "Fascial fibroblasts resemble features of fibroblasts derived from hypertrophic scars and keloids, including high expression of NOV (nephroblastoma overexpressed, or CCN3), CD26 (DPP4), and FAP (fibroblast activating protein) to produce more of the proteoglycan versican but less collagenase (MMP1)." (PMID 34445709, 2021).
multiple myeloma (9 papers, 2011 to 2026). "In monocyte/macrophage‐derived osteoclasts, DPP‐4/CD26 expression is progressively upregulated under certain pathological conditions, such as osteolytic bone lesions from multiple myeloma, osteosarcoma, adenocarcinoma." (PMID 41566690, 2026). "In this paper, we show that DPP4 inhibitors also induced cell death in multiple human myeloma cells." (PMID 31792328, 2019). "Therefore, herein we initially investigated the therapeutic efficacy of DPP4 inhibitors on multiple myeloma cells, work which subsequently led to the interesting findings indicating that DPP8 is a novel therapeutic target for multiple myeloma." (PMID 31792328, 2019). "Among five DPP4 inhibitors, only two of them, vildagliptin and saxagliptin, exhibited apparent cytotoxic effects on myeloma cell lines, without any difference in suppression of DPP4 activity." (PMID 31792328, 2019).
myocardial ischemia (9 papers, 2014 to 2023). A disorder of cardiac function caused by insufficient blood flow to the muscle tissue of the heart. "In conclusion, our study reveals for the first time that DPP4 activity decreases during cardiac surgery dependent on the duration of surgery-induced myocardial ischemia, and that low post-operative DPP4 activity levels are associated with worse patient outcome during ICU stay." (PMID 30087386, 2018). "The effect of DPP4 antagonism was studied in models of myocardial ischemia/reperfusion (I/R) and infarction in normoglycemic and hyperglycemic animal models of CV disease by genetic deletion of DPP4 or by using DPP4i." (PMID 35945358, 2022). "It has also been shown in preclinical studies that both GLP-1 receptor agonists and DPP-4 inhibitors exhibit cardioprotective effects in animal models of myocardial ischemia and ventricular insufficiency through incompletely characterized mechanisms." (PMID 35782875, 2022). "As DPP4 oxidation by hydrogen peroxide reduces DPP4 activity, low post-operative DPP4 activity levels likely reflect the severity of myocardial ischemia through the generation of reactive oxygen species." (PMID 30087386, 2018). "Further studies are necessary to investigate sex‐specific effects of DPP4 inhibition in myocardial ischemia, and whether sex‐hormone interactions may play a role." (PMID 37300400, 2023). "Interestingly, DPP-4 inhibition improves cardiac function and reduces myocardial ischemia through SDF-1a/CXCR4-mediated STAT3 signaling and exerts an antiapoptotic effect on HUVEC under hypoxic conditions." (PMID 35615279, 2022). "Furthermore, a correlation analysis revealed a larger decrease in intra-operative DPP4 activity for an increased duration of aortic cross clamping, representing the duration of myocardial ischemia during surgery." (PMID 30087386, 2018). "However, in cardiac pathology, it seems that DPP4 is implicated in high levels of NPs as it was found that genetic deletion of DPP4 improved the elevated levels of ANP and BNP in rats subjected to myocardial ischemia/reperfusion." (PMID 35945358, 2022). "As DPP-4 activity is highest in the kidney, increased DPP-4 activity in CKD may worsen myocardial ischemia." (PMID 30823876, 2019). "Although several previous studies have shown that DPP4 inhibitors are capable of offering cardiovascular protection and preserving cardiac functions from myocardial ischemia, the precise mechanisms involved have not been extensively investigated." (PMID 25496837, 2014). "Furthermore, increased arteriogenesis with DPP4 inhibition has been seen in hind limb ischemia animal models, though similar studies in coronary circulation in the setting of myocardial ischemia are lacking." (PMID 37300400, 2023).
sarcopenia (9 papers, 2018 to 2025). Progressive decline in muscle mass due to aging which results in decreased functional capacity of muscles. "We also sought to identify associations of use of DPP-4 inhibitors, statins, or vitamin D analogs with sarcopenia." (PMID 29447254, 2018). "Considering the possible efficacy of insulin, dipeptidyl peptidase 4 inhibitors (DPP4-I) are good candidates for sarcopenia treatment because they stimulate insulin secretion in a blood glucose-level dependent manner." (PMID 34063269, 2021). "In conclusion, loop diuretic use was associated with increased risk of sarcopenia in patients with NDD-CKD, whereas DPP-4 inhibitor, RAAS inhibitor, statin, and vitamin D analog use was not." (PMID 29447254, 2018). "Insulin might promote myoblast activation and division, which would constitute the sarcopenia preventive effect of DPP4 inhibitors." (PMID 32868771, 2020). "Hence, DPP-4 inhibitors are generally considered neutral with respect to sarcopenia." (PMID 39463580, 2024). "DPP-4 inhibitors have already replaced sulfonylureas as the second option for T2DM treatment and have also been investigated against other conditions, such as sarcopenia." (PMID 36672642, 2023). "The current secondary analysis revealed that postprandial plasma aGLP-1 and aGIP excursions modified by 24-week add-on treatment with an αGI miglitol and/or a DPP-4 inhibitor sitagliptin did not affect skeletal muscle mass regulation in T2D patients without sarcopenia." (PMID 37176545, 2023).
systemic lupus erythematosus (9 papers, 2007 to 2026). An autoimmune multi-organ disease typically associated with vasculopathy and autoantibody production. "MRL/lpr lupus-prone mice were treated with the DPP-4 inhibitor linagliptin, either alone or in combination with the CXCL12/CXCR4 axis antagonist AMD3100." (PMID 41601976, 2026).
T-cell lymphoma (9 papers, 2009 to 2025). "For instance, anti-DPP4 mAbs (e.g., IF7 and 14D10) inhibited the growth of DPP4-positive tumor cells in T-cell lymphoma models." (PMID 40597436, 2025).
urinary tract infection (9 papers, 2008 to 2023). "Meta-analysis studies showed that the use of DPP4 inhibitor treatment significantly increases the incidence of upper respiratory tract and urinary tract infections." (PMID 35413090, 2022). "Additionally, meta-analysis studies showed that after treatment with DPP4 inhibitors, upper respiratory tract and urinary tract infections increased significantly." (PMID 35413090, 2022). "The risk of urinary tract infection was not increased in SGLT2i/DPP4i; however, the risk of genital infection increased upon adding SGLT2 inhibitors to pre-existing DPP4 inhibitors." (PMID 29535389, 2018).
anemia (8 papers, 2019 to 2024). A reduction in the number of red blood cells, the amount of hemoglobin, and/or the volume of packed red blood cells. "Furthermore, hypoglycemic agents such as metformin, thiazolidinediones (TZD), dipeptidyl peptidase-4 (DPP-4) inhibitor were also confirmed to be associated with anemia." (PMID 36755908, 2023). "Patients in the tirzepatide group also had lower prevalence rates of CKD or anemia, and fewer were using statins, biguanides, sulfonylureas, dipeptidyl peptidase 4 inhibitors, β-blockers, ARBs, or calcium channel blockers." (PMID 39133485, 2024).
Crohn disease (8 papers, 2007 to 2025). A gastrointestinal disorder characterized by chronic inflammation involving all layers of the intestinal wall, noncaseating granulomas affecting the intestinal wall and regional lymph nodes, and transmural fibrosis. "Host- and microbiota-derived DPP4 synergistically drive intestinal fibrosis in Crohn’s disease (CD)." (PMID 41334589, 2025). "DPP4 tissue expression and activity have been investigated in small intestinal disease, such as Crohn's disease and celiac disease; however, tissue expression and activity profiles of all DPPs during IBD have not been characterized previously." (PMID 35060938, 2022). "While circulating DPP-4 activity and the amount of the enzyme in plasma and colon is reduced in patients with active Crohn's disease, DPP-4 positive lymphocytes are higher in patients compared to healthy controls." (PMID 30186247, 2018). "In a separate study, the expression of dipeptidyl peptidase-4 (that inactivates GLP-1) was found to be significantly reduced in tissue and plasma from patients with active Crohn’s Disease, potentially elevating and enhancing the effects of GLP-1." (PMID 29813107, 2018).
diabetic cardiomyopathy (8 papers, 2014 to 2025). Diabetic cardiomyopathy is a disorder of the heart muscle in people with diabetes. "We investigated whether evogliptin® (EVO), a DPP-4 inhibitor, could protect against diabetic cardiomyopathy (DCM) and the underlying mechanisms." (PMID 37009790, 2023). "This is the first study to demonstrate that DPP-4 inhibition by evogliptin prevents diabetic cardiomyopathy by reducing cardiac lipotoxicity, mitochondrial damage, and fibrosis in db/db mice." (PMID 37009790, 2023). "Therefore, the DPP-4 inhibitor may be a promising drug for the prevention of diabetic cardiomyopathy." (PMID 25285158, 2014). "Therefore, DPP-4 inhibitor seems to have cardioprotective effects independent of glucose control and may have a role in the prevention of diabetic cardiomyopathy." (PMID 25285158, 2014). "For example, dipeptidyl-peptidase 4, a potential therapeutic for diabetic cardiomyopathy, failed to yield positive outcomes in clinical trials despite promising results shown in preclinical animal models." (PMID 35388880, 2023). "In our present study, Dpp4 was down-regulated; therefore it does not seem to be a major and/or necessary regulator in the development of diabetic cardiomyopathy in non-obese T2DM." (PMID 27496100, 2016).
gout (8 papers, 2021 to 2025). A condition characterized by painful swelling of the joints, which is caused by deposition of urate crystals. "We observed a significant 0.85-fold (95% CI, 0.74-0.97; P = .02) risk for gout in patients receiving SGLT2 inhibitors compared with DPP4 inhibitors, especially for those receiving empagliflozin (HR, 0.83; 95% CI, 0.69-0.98; P = .03)." (PMID 34797368, 2021). "The findings of this study suggest that use of SGLT2 inhibitors in patients with T2DM is associated with a lowered gout incidence of 11% compared with DPP4 inhibitors." (PMID 34797368, 2021). "In this study, we used Taiwan’s National Health Insurance database to assess the association between SGLT2 inhibitor use and the risk of gout incidence compared with use of dipeptidyl peptidase 4 (DPP4) inhibitors in patients with T2DM." (PMID 34797368, 2021). "The findings of this study showed that use of SGLT2 inhibitors in T2DM was associated with a lower risk of gout incidence compared with use of DPP4 inhibitors in a national Taiwanese cohort." (PMID 34797368, 2021). "When potential risk factors were adjusted in the propensity score–matched population, use of SGLT2 inhibitors was associated with a lower risk of gout (HR, 0.89; 95% CI, 0.82-0.96) compared with DPP4 inhibitors, particularly for patients receiving dapagliflozin (HR, 0.86; 95% CI, 0.78-0.95)." (PMID 34797368, 2021). "The findings of this study suggest that patients with T2DM who are receiving SGLT2 inhibitors may have a lower risk for gout compared with those receiving DPP4 inhibitors." (PMID 34797368, 2021). "After considering potential risk factors, dapagliflozin users had an HR of 0.86 (95% CI, 0.78-0.95, P = .002), and empagliflozin users had an HR of 0.93 (95% CI, 0.84-1.03, P = .16) for incidence of gout compared with DPP4 inhibitor users." (PMID 34797368, 2021). "Notably, SGLT2i have also been associated with lower risk of recurrent gout flares compared to GLP-1 receptor agonists and DPP-4 inhibitors in type 2 DM patients." (PMID 41189618, 2025). "Treatment with DPP4 inhibitors also reduced sUA levels (5.2±1.3 mg/dL vs. 5.9±2.2mg/dL, p=0.05).Fig. 2displays trendsof eGFR for patients with T2DM and gout treated with DPP-4 inhibitors vs. controlgroup." (PMID 40300646, 2025). "Some novel antidiabetic agents, such as dipeptidyl peptidase-4 inhibition (DPP4I), reduced UA levels in patients with T2DM and had additional benefits for gout." (PMID 40444241, 2025). "The cumulative incidence of gout between the propensity score–matched populations was 4.63% for SGLT2 inhibitors and 5.25% for DPP4 inhibitors (log-rank P = .005)." (PMID 34797368, 2021). "During a follow-up of approximately 2.5 years, we observed differences in the overall gout incidence: 20.26 per 1000 patient-years for SGLT2 inhibitor users and 24.30 per 1000 patient-years for DPP4 inhibitor users." (PMID 34797368, 2021). "The overall gout incidence was 20.26 per 1000 patient-years for SGLT2 inhibitor users and 24.30 per 1000 patient-years for DPP4 inhibitor users." (PMID 34797368, 2021). "Our findings suggest that DPP-4 inhibitors may provide benefits beyond glycemiccontrol in patients with T2DM, gout, and CKD." (PMID 40300646, 2025). "A network meta-analysis, including DPP4 inhibitors among other newer glucose-loweringdrugs, found no reduction in gout flares among patients treated with DPP4inhibitors." (PMID 40300646, 2025). "The current study aimed to determine the incidence of gout attacks over six years inpatients with gout and T2DM treated or not with DPP-4 inhibitors." (PMID 40300646, 2025). "While treatment with DPP4 inhibitors did not affect the mortality rate in the studygroups, it significantly affected the survival rates among those patients with CKDwho were diagnosed with T2DM and gout." (PMID 40300646, 2025).
Hyperinsulinemia (8 papers, 2014 to 2025). An increased concentration of insulin in the blood. "Our data suggest that rs12617336 and rs17574 DPP4 minor alleles could be envisaged as protective genetic markers for hypoalphalipoproteinemia, IR, and hyperinsulinemia." (PMID 34178021, 2021).
ischemic stroke (8 papers, 2015 to 2025). A stroke disorder caused by obstruction of blood flow to the brain, due to thrombotic (local blood clot formation) or embolic (due to a blood clot or other material traveling from another site) event. "From a cardiovascular perspective, DPP-4 inhibitors have demonstrated protective effects against ischemic stroke, improved neurovascular function, and a reduction in major adverse cardiovascular events (MACEs)." (PMID 40771927, 2025). "In conclusion, our data suggest that, compared with a DPP-4 inhibitor plus metformin, treatment with a sulfonylurea derivative plus metformin was associated with increased risks of total CVD, MI, and ischemic stroke." (PMID 25992614, 2015). "The survival benefits may be attributable to significantly fewer ischemic stroke events among DPP-4 inhibitor users due to neuroprotective effects." (PMID 34496858, 2021). "Among the patients treated with a DPP-4 inhibitor plus metformin, the crude incidence per 1,000 person-years was 15.75 for total CVD, 1.45 for MI, 0.88 for HF, and 4.65 for ischemic stroke." (PMID 25992614, 2015).
Myocardial fibrosis (8 papers, 2013 to 2025). "We therefore sought to evaluate the effect of the DPP-4 inhibitor sitagliptin on myocardial fibrosis, and insulin signaling in chronic myocardial ischemia using a swine model." (PMID 39074126, 2024). "DPP4 may contribute to myocardial fibrosis by promoting stromal cell activation and extracellular matrix deposition, and it may exacerbate chronic inflammation through modulation of chemokines and cytokines." (PMID 40904650, 2025). "It has been well demonstrated that DPP-4 inhibitors reduce fibrosis and modulate insulin signaling in several pathways; however, our study represents the first attempt to study the changes in myocardial fibrosis and insulin signaling with SIT in a swine model of chronic myocardial ischemia." (PMID 39074126, 2024). "This is supported by a study with 10-week-old db/db mice, where the treatment with a DPP-4 inhibitor extenuated the expression of TGF-β1 and reduced myocardial fibrosis." (PMID 24004910, 2013). "Additionally, saxagliptin-mediated dipeptidyl peptidase-4 (DPP-4) inhibition elevates circulating stromal cell-derived factor-1α (SDF-1α), potentially exacerbating myocardial fibrosis and inflammatory responses." (PMID 40538809, 2025).
periodontitis (8 papers, 2017 to 2025). An acute or chronic inflammatory process that affects the tissues that surround and support the teeth. "Host-derived DPP-4 activity: Multiple observational studies consistently reported elevated DPP-4 levels in saliva, gingival crevicular fluid, and gingival tissues in periodontitis patients." (PMID 41307071, 2025). "Specific genes, including DPP-4, showed statistically significant differences between the healthy volunteers and patients with severe periodontitis." (PMID 38337597, 2024). "Other than ACE2, BMAL1, CD147, FURIN, and TMPRSS2, more genes, including CD26(DPP4), IFITM3, HLA, ABO, SLC6A20, GSTT1-M1, and DBP, have also been implicated in SARS-CoV-2 and periodontitis." (PMID 36366382, 2022). "Our results revealed that DPP-4 levels were higher and significantly different in all groups of periodontitis patients compared with those from the control group, with the upregulation of this compound suggesting that its levels are associated with periodontitis’ inflammatory activity." (PMID 40429343, 2025). "Role of DPP-4, periodontopathic bacteria, and molecular pathways in periodontitis." (PMID 41307071, 2025). "The study concluded that P. gingivalis and periodontitis are associated with DPP-4 activity but not alanine aminopeptidase’s activity." (PMID 38337597, 2024). "DPP4 is a clinical periodontal biomarker that has been shown to be positively correlated with the prevalence of P. gingivalis as well as disease severity in periodontitis patients." (PMID 38003760, 2023). "Although DPP-4 activity in the oral mucosa of patients with oral cancer remains unknown, it might also be high as observed in patients with periodontitis." (PMID 29228568, 2017). "A recent study suggested that the activity of DPP-4 in the saliva of patients with periodontitis was significantly elevated and positively correlated with all clinical parameters of periodontitis including the prevalence of infection with Porphyromonas gingivalis." (PMID 29228568, 2017). "We found robust correlations between GCF biomarkers (DPP-4 and Gal-3) and clinical measures (GI and PPD), suggesting that these molecules reflect periodontitis severity and may participate in its pathogenesis." (PMID 40429343, 2025).